YY1AP1 (YY1 associated protein 1)
Description:
Associates with the INO80 chromatin remodeling complex, which is responsible for transcriptional regulation, DNA repair, and replication. Enhances transcription activation by YY1. Plays a role in cell cycle regulation.
Synonyms: HCCA2; YY1AP; YAP; GRNG; HCCA1
Tractability: PROTAC: ubiquitination databases record sites on it.
Gene: Protein-coding gene on chromosome 1 (155,659,446 to 155,689,334, reverse strand). Ensembl gene ENSG00000163374.
Subcellular location: Cytoplasm; Nucleus; Nucleus, nucleoplasm; Nucleus, nucleolus
Subcellular location (Human Protein Atlas): Nucleoli fibrillar center
Gene Ontology:
Molecular function: protein binding
Biological process: cell differentiation; cell population proliferation; regulation of cell cycle
Cellular component: cytoplasm; Ino80 complex; nucleolus; nucleoplasm; nucleus
Genetic constraint (gnomAD): Loss-of-function variants: 42 observed, 41.2 expected, observed/expected ratio (o/e) 1.02, 90% interval 0.8 to 1.32. The upper end of that interval is the gene's LOEUF score, 1.32, which puts it in group 5 of 6, group 1 being the genes least tolerant of losing a copy. Missense variants: 810 observed, 918.71 expected, observed/expected ratio (o/e) 0.88, 90% interval 0.83 to 0.93. Synonymous variants: 292 observed, 339.06 expected, observed/expected ratio (o/e) 0.86, 90% interval 0.78 to 0.95.
Homologues: Orthologues: chimpanzee YY1AP1 (94% identical), guinea pig Gon4l (77% identical), rat Gon4l (72% identical), mouse Gon4l (72% identical). Paralogues in human: GON4L (93% identical).
Diseases named in the same sentence as YY1AP1 in open-access papers:
YY1AP1 is named in the same sentence as 42 diseases in open-access papers, as found by Europe PMC text mining. Sharing a sentence is not in itself a finding about the gene and the disease. The quoted sentences say what the papers report.
grange syndrome (5 papers, 2019 to 2026). Grange syndrome is characterized by stenosis or occlusion of multiple arteries (including the renal, cerebral and abdominal vessels), hypertension, brachysyndactyly, syndactyly, increased bone fragility, and learning difficulties or borderline intellectual deficit. "WES revealed a c.724C>T (p.Gln242*) nonsense variant in the YY1AP1 gene, previously implicated in Grange syndrome and FMD-like syndrome, which involves vascular abnormalities." (PMID 41282474, 2025). "Recessive pathogenic variants in YY1AP1 have been reported in association with Grange syndrome (OMIM 607860)." (PMID 31463572, 2019). "According to the OMIM database, the YY1AP1 gene is associated with Grange syndrome (ID 602531)." (PMID 33971976, 2021).
breast carcinoma (2 papers, 2020 to 2025). "GLS, YY1AP1, FBXO22, KLC1, CUL4A, KITLG, and CYRIB are changed by AS that may be linked to the emergence of breast cancer." (PMID 40384436, 2025).
fibromuscular dysplasia (2 papers, 2023 to 2025). A disorder characterized by fibrous thickening of the arterial wall resulting in narrowing of the arterial lumen. "Pathogenic variants in YY1AP1 are associated with a distinct vascular phenotype resembling fibromuscular dysplasia and are frequently accompanied by skeletal and neurodevelopmental abnormalities." (PMID 41465473, 2025).
hepatocellular carcinoma (2 papers, 2019 to 2020). A malignant tumor that arises from hepatocytes. "YY1AP1 is a co-activator of YY1, and activates transcription of stemness regulators in hepatocellular carcinoma." (PMID 31824839, 2019).
renal carcinoma (2 papers, 2019 to 2022). A carcinoma arising from the epithelium of the renal parenchyma or the renal pelvis. "Subsequently, the renal carcinoma cells were treated with Stattic (a STAT3 inhibitor) and Verteporfin (a YY1AP1 inhibitor) for 24 h." (PMID 31354472, 2019).
brachydactyly (1 paper, 2020). A disease characterized by the presence of brachydactyly, including syndromic and non-syndromic forms. "The case with 2 YY1AP1 variants has FMD, renal artery stenosis, brachydactyly, and migraines." (PMID 33125268, 2020).
dyslipidemia (1 paper, 2021). "Besides, we found some evidence to explain her dyslipidemia as a polygenic trait concurring with vascular lesions which are characteristic of YY1AP1 LOF variants." (PMID 33971976, 2021). "Since dyslipidemia is not a feature previously associated with YY1AP1 variants, we investigated other causes of dyslipidemia on a whole genome level, especially in genes associated with monogenic familial hypercholesterolemia (FH)." (PMID 33971976, 2021).
Intellectual disability (1 paper, 2026). "Our findings highlight the importance of considering YY1AP1-related pathology in the differential diagnosis of intellectual disability and syndactyly, even in the absence of vascular features." (PMID 41882341, 2026).
multiple myeloma (1 paper, 2023). "Additionally, investigating the function and significance of YY1AP1 in multiple myeloma, including its interactions with other genes and pathways, can provide valuable insights for disease progression and treatment strategies." (PMID 37608887, 2023).
Obesity (1 paper, 2021). Accumulation of substantial excess body fat. "For DE RNAs of obesity in SAT, 4 mRNAs (ENO2, YY1AP1, FAP, IL10RB) and 1 miRNA (hsa-miR-425) were found." (PMID 34621242, 2021). "For DE RNAs of obesity-related ccRCC in SAT, 4 mRNAs (ENO2, YY1AP1, FAP, IL10RB) and 1 miRNA (hsa-miR-425) were eligible for the following risk score analyses." (PMID 34621242, 2021).
tumor (4 papers, 2019 to 2022). "Dysregulation of the Hippo signaling pathway can lead to pathogenesis, and a key downstream protein, YY1AP1, is generally overexpressed in tumor tissues." (PMID 31354472, 2019).
cancer (3 papers, 2020 to 2022). A tumor composed of atypical neoplastic, often pleomorphic cells that invade other tissues. "The signal transducer and activator of transcription 3 (STAT3) and YY1-associated protein 1 (YY1AP1) are two oncogene factors in cancer cells." (PMID 32380783, 2020). "The evidence presented here reveals that the synthetic lethal interaction between miR-1193 inhibition and DNA-PKcs deficiency significantly suppresses cell growth and promotes apoptosis through the YY1AP1/YY1/FEN1 pathway in M059J cancer cells." (PMID 32732911, 2020).
YY1AP1 also shares sentences with these, for which no sentence is quoted: osteosarcoma (2 papers); artery disease (1); cervical cancer (1); chronic pancreatitis (1); dilated cardiomyopathy (1); dissection (1); endometrial cancer (1); familial hypercholesterolemia (1); gestational diabetes mellitus (1); glioblastoma (1); head and neck squamous cell carcinoma (1); Holt-Oram syndrome (1); hypopharyngeal squamous cell carcinoma (1); Hyporeflexia (1); keratoconus (1); lung carcinoma (1); macular degeneration (1); melanoma (1); migraines (1); muscular dystrophy (1); osteoarthritis (1); ovarian carcinoma (1); pancreatic ductal adenocarcinoma (1); paraplegia (1); Renal artery stenosis (1); retinopathy (1); spinal muscular atrophy (1); thyrotoxicosis (1); uveal melanoma (1); virus infection (1).